MX1 (MX dynamin like GTPase 1)
Diseases named in the same sentence as MX1 in open-access papers (continued):
Sharing a sentence is not in itself a finding about the gene and the disease.
cancer (55 papers, 2007 to 2026). A tumor composed of atypical neoplastic, often pleomorphic cells that invade other tissues. "In human cancer this pattern is discussed to protect certain malignancies from radiotherapy and mx1 has been linked with a poor prognosis in breast and prostate cancer as well as colorectal carcinoma in humans." (PMID 40271486, 2025). "Analysis of the human MX1 gene in the Catalog of Somatic Mutations in Cancer (COSMIC) database identified 122 mutations across many common cancers." (PMID 39285636, 2024). "Recently, the expression of mx1 has been reported in some human cancers and linked to their biological behavior albeit the exact role remains undetermined." (PMID 38962703, 2024). "Mx1 gene mutations in the coding region for MxA have been discovered in many types of cancer, suggesting potential biological associations between mutations in MxA protein and corresponding cancers." (PMID 26411585, 2015). "Genes that have been previously associated with MD and various other cancers showed differential marks that are either MD-induced (MX1, CTLA-4, EAF2 and GAL) or line-specific (IGF2BP1 and MMP2)." (PMID 23072359, 2012). "Further, the expression of MX dynamin like GTPase 1 (mx1) in cancer is linked to immune evasion." (PMID 40271486, 2025). "MX1—The MX1 gene encodes a GTPase called MxA that inhibits motility and invasiveness of cancer." (PMID 38304289, 2023). "Finally, it is worth noting that in addition to aggressive liver injury in the Mx1-Cre; Moff/f mice, the gene pathway associated with cancer was also modestly enriched in Mof null liver and NASH patients." (PMID 33376138, 2021). "Cancer-associated Mx1 mutations were collected and screened from the COSMIC database." (PMID 26411585, 2015). "MX1, also known as the interferon-induced GTP-binding protein Mx1, is crucial in inflammation and cancer." (PMID 38972952, 2024). "We also found that MUC1-C is necessary for the expression of IFN-stimulated genes (ISGs), including IFIT1/3, OAS1/3, IFITM1, IFI44L and MX1, that promote DNA damage resistance, chronic inflammation and cancer progression." (PMID 34657147, 2022). "In vitro experiments revealed that MX1 was able to inhibit cancer cell migration and reduce metastasis of prostate and melanoma cancer." (PMID 36339597, 2022). "In TNBC patients, IFNβ1 expression in CAFs correlated with cancer cell expression of MX1, a marker of activated IFN signalling." (PMID 33398063, 2021). "From a functional point of view, genes involved in interferon signaling and cytotoxicity (IFIT1, IFIT3, and MX1) are upregulated in COVID/cancer cohort." (PMID 34716309, 2021). "Such ICI resistance was described to rely on epigenomic changes on cancer cells, the expression of various ISGs (i.e., Tnfrsf14, Lgals9, MhcII, Ifit, Mx1), and induction of multiple T cell inhibitory receptor networks." (PMID 34571733, 2021). "We show that breast CAFs protect claudin-low TNBCs from chemotherapy through secretion of IFNβ1 leading to paracrine activation of IFN signalling in the cancer cells, as denoted by upregulation of MX1." (PMID 33398063, 2021). "MX1 contributes to the progression of cancers with different attributions, as noticed in various cancers." (PMID 32350677, 2020). "The progression initiates toward the metastatic processes in which cell proliferation, migration and death by the cancer are sustained or inhibited by MX1." (PMID 32350677, 2020). "MX1 also has a role in the inhibition of motility and invasiveness in some cancers, such as prostate carcinoma and melanoma." (PMID 32350677, 2020). "MX1 is overexpressed and appeared to play a role in a variety of cancers but its effect remains controversial." (PMID 32350677, 2020). "MX1 is a key mediator of the interferon-induced antiviral response and is downregulated in cancer cells." (PMID 30150751, 2018).
cancer (continued). "Similar to the results obtained with the mouse carcinomas, marked upregulation of human Ifnb1 and Mx1 was seen after irradiation with 8 Gy X 1, which was further increased with 8 Gy X 3, while 20 Gy upregulated Trex1." (PMID 28598415, 2017). "Here, reconstitution of wild type BRCA1 plasmid in both MX1 and HCC1937 showed selective cytotoxic activity of PB against BRCA1 mutated cancer cells." (PMID 27220670, 2016). "Several genes related to interferon signaling were downregulated in the 'both' cancers, most significantly, the prototypic type I interferon response gene MX1 (also named MXA)." (PMID 17280610, 2007). "The presence of mx1 is plausibly part of a yet undefined role in cancer biology." (PMID 38962703, 2024). "Nonetheless, their finding solely showed that the αvβ6 integrin has profound effects on the microenvironment by preventing induction of the STAT1/MX1/2 signaling pathway in donor cancer cells and their exosomes, and the investigation of exosomal αvβ6 integrin in PCa patients was not conducted." (PMID 39538297, 2024). "As yet, little is known about the regulatory role of MX1 in cancer." (PMID 37686559, 2023). "Although MX1 protein activity craves for antiviral activities in the immunity system, it aids in bringing about a signal that articulates a significant contribution to cancer progression and response to treatments, such as chemotherapy procedures." (PMID 32350677, 2020). "MX1 has been demonstrated to play a role in various human cancers." (PMID 32350677, 2020). "It was observed that reduced MX1 level can suppress apoptosis during cancer development." (PMID 32350677, 2020). "Importantly, such resistance to inflammation-associated colon tumorigenesis in Mx1-Cre;Gankyrinf/f mice was associated with a significant reduction of pro-inflammatory responses (IL-17 and TNF-α) and expression of cancer stem cell markers (Bmi1 and Sox9)." (PMID 28160571, 2017). "MX1 gene product promotes cell death induced by apoptotic stimuli and therefore low levels of MX1 protein might contribute to apoptosis resistance during cancer development." (PMID 24358304, 2013). "In addition, IFNs have been reported to repress invasion of cancer cells via MX1.We therefore measured the effect of IFNβ on the migratory capacity of cancer cells." (PMID 23630584, 2013). "In addition, mRNA levels of Tnf and Mx1 (an interferon-stimulated gene linked to Ifnb1 expression) were upregulated in MakA-treated tumors, suggesting a pro-inflammatory TME with enhanced anti-cancer potential." (PMID 41326332, 2025). "However, MX1 appears to have different effects in other cancers." (PMID 32350677, 2020). "In particular, the expression levels of genes, such as IFI6, MX1, IFIT1, IFIT3, ISG15, OAS1, and OAS2, which belong to the cancer-promoting ISG subset IRDS, were markedly increased." (PMID 35618021, 2022). "To that end, we initiated an interferon response by co-cultivating CAFs and carcinoma cells, leading to the elevation of IFN targets MX1 and STAT1." (PMID 23630584, 2013). "As a result, MUC1-C was also necessary for expression of (i) OAS1, which attenuates PAR synthesis during DNA repair and promotes the ability of cancer cells to survive replicative stress, and (ii) IFIT1-3, MX1 and BST2, among others, which confer DNA damage resistance." (PMID 35681561, 2022). "Indeed, the expression of CCL8, IFIT1, IFIT3, IFI27, MX1, and RSAD2 has previously been considered favorably prognostic in several types of cancer." (PMID 36180872, 2022). "Control animals carrying only R26PR, Mx1-cre (with pIpC injection), MMTV-cre or no transgenic/targeted alleles [wild type (WT)] did not develop cancer or any other disease after 6 months of aging." (PMID 24046360, 2013).
bacterial infections (25 papers, 2015 to 2026). "Bacterial infection significantly upregulated mRNA expression levels of Isg15, Mx1, Mx2, Irf-3, Irf-7, Tlr-2, Tnf-α, Cxcl-1, and Il-6 genes." (PMID 37929187, 2023). "Of note, many of these genes encode antiviral proteins (e.g., Mx1/2, IFITs, OAS) that to date have a less well-defined role in bacterial infections." (PMID 28900269, 2017). "In addition, a further 12 ISGs of 380 tested ISGs including STAT1, STAT2, JAK1, IRF9, IRF2, IRF7 are key elements of IFN signaling, and classical and well-known ISGs such as ISG15, PKR, MX1, IFIT1, PML, IFI27 play key roles in viral or bacterial infections." (PMID 30717477, 2019).
infectious disease (5 papers, 2013 to 2022). A disorder directly resulting from the presence and activity of a microbial, viral, or parasitic agent in humans. "Many genes in the KLHDC7B-downregulated dataset are related, such as STAT1, IFIT3, and MX1, with the antimicrobial or infectious disease properties showing decreased expression." (PMID 30150751, 2018).
myopathies (4 papers, 2017 to 2026). "Overall, MX1 is a valuable tissue biomarker for interferon-mediated myopathies, with potential applications in diagnosis, disease activity assessment, and monitoring systemic progression." (PMID 41769532, 2026). "Using microarrays, IFIG expression levels (including ISG5, Mx1, OAS1, IFIT4, IFIT1, IFI44, OAS3, OAS2, IRF7, and IFI27) in muscle samples were higher in DM than in other inflammatory myopathies, such as inclusion body myositis, polymyositis, necrotizing myopathy, and myopathies with inflammation." (PMID 36979843, 2023).
neurologic disorders (3 papers, 2016 to 2022). "Indeed, identified genes are implicated in viral (SEC14L1, JMJD6, SRSF2, TMPRSS2, MX1, MX2) bacterial (COL8A1, SPIRE1), and neurological disorders (MFSD11, METTL23, CTTNBP2, BACE2, IMPA2, MPPE1 and GNAL), or in the functions of the Golgi complex (MGAT5B), organelle where viral envelope is occurred." (PMID 35581286, 2022). "In conclusion, based upon the results of our comprehensive analysis of HHV-6A infected HA1800 cells, we revealed several genes correlated with neurologic disorders, especially CTSS, PTX3, CHI3L1, Mx1, CXCL16, BIRC3, and BST2 genes." (PMID 27344170, 2016). "Another study representing the first transcriptome sequencing study proposed the association of seven genes (CTSS, SERPINA1, NPTX1, PTX3, CHI3L1, SERPINA3, and MX1) as “the missing link” to explain the correlation between HHV-6A infection and neurological diseases." (PMID 35683449, 2022).
inflammation (2 papers, 2013 to 2025). Aberrant reaction of the microcirculation characterized by movement of fluid and leukocytes from the blood into extravascular tissues. "We also reexamined the relationship between titer, airway inflammation and weight loss, to determine if our earlier observation, which linked both titer and airway inflammation as significant predictors of weight loss was independent of Mx1 status." (PMID 23468633, 2013).
hematologic diseases (1 paper, 2020). "Somatic Mx1-Cre–mediated activation in the hematopoietic compartment showed that KrasP34R and KrasT58I expression had distinct signaling effects, despite causing a similar spectrum of hematologic diseases." (PMID 32990679, 2020). "Some Mx1-Cre KrasLSL-T58I/+ and Mx1-Cre KrasLSL-P34R/+ mice developed systemic hematologic disease and became sick before 12 months of age, and both mutant strains had a significantly shorter median survival." (PMID 32990679, 2020).
renal disease (1 paper, 2008). "The clinical characteristics of IFIT4 are similar to those of another IFIG, namely Mx1, whose expression is also positively associated with autoantibodies against SM/RNP and dsDNA, but not with SLEDAI or the presence of renal disease." (PMID 18706081, 2008).
MX1 also shares sentences with these, for which no sentence is quoted: respiratory infections (7 papers); Respiratory tract infection (4); viral diseases (4); interstitial lung disease (3); leukocytosis (3); myositis (3); SARS-CoV infection (3); subacute sclerosing panencephalitis (3); Thrombocytopenia (3); Alzheimer disease (2); atopic dermatitis (2); biliary atresia (2); cervical cancer (2); infiltrating breast cancer (2); juvenile dermatomyositis (2); lupus erythematosus (2); lymph node metastases (2); multiple myeloma (2); renal cell carcinoma (2); Sepsis (2); upper respiratory tract infection (2); adenocarcinoma (1); astrocytomas (1); Atrophy (1); autoimmune encephalitis (1); bacterial pneumonia (1); benign prostatic hyperplasia (1); bladder cancer (1); bovine respiratory disease complex (1); calcinosis (1).
A further 74 diseases each share a sentence with MX1 in 1 paper.